PVT1 (Pvt1 oncogene)
Diseases named in the same sentence as PVT1 in open-access papers (continued):
Sharing a sentence is not in itself a finding about the gene and the disease.
osteosarcoma (continued). "Therefore, silencing PVT1 by siRNA suppresses proliferation, migration and invasion and promotes cell cycle arrest and apoptosis via miR-195 in osteosarcoma cells." (PMID 27813492, 2016). "Furthermore, the results showed that the mRNA expression level of PVT1 was higher in metastatic osteosarcoma tissues than primary osteosarcoma tissues (P < 0.05)." (PMID 27813492, 2016). "Therefore, lncRNAs are considered important therapeutic targets for diseases, but the mechanism and function of the lncRNA PVT1 in osteosarcoma are poorly understood." (PMID 27813492, 2016). "The results also indicated that PVT1 reduced the survival rate of osteosarcoma patients (P < 0.05)." (PMID 27813492, 2016). "Moreover, silencing PVT1 by siRNA inhibited proliferation, migration and invasion and promoted apoptosis and cell cycle arrest in osteosarcoma cells via miR-195." (PMID 27813492, 2016). "Furthermore, we demonstrated that silencing PVT1 inhibited proliferation, migration and invasion and promoted apoptosis and cell cycle arrest in osteosarcoma cells." (PMID 27813492, 2016). "Thus, the potential roles of lncRNA PVT1 in the EMT of osteosarcoma cells were analyzed." (PMID 32960485, 2021). "Since the long non-coding RNA PVT1 has been reported to be upregulated in osteosarcoma cells and contributes to its growth and metastasis, we aim to investigate whether BMSC-derived exosomes promote osteosarcoma growth and metastasis via transporting PVT1 into osteosarcoma cells." (PMID 31699956, 2019). "However, whether BMSC-EXOsi-PVT1 could compete with BMSC-EXO for the uptake by osteosarcoma cells deserves further investigations." (PMID 31699956, 2019). "Therefore, our study demonstrated that PVT1 may be a therapeutic target for treatment of osteosarcoma." (PMID 27813492, 2016). "Therefore, we speculated that PVT1 may play a vital role in the development and progression of osteosarcoma." (PMID 27813492, 2016). "Our study demonstrated that PVT1 may be a therapeutic target for the treatment of osteosarcoma." (PMID 27813492, 2016). "Our research also demonstrates that PVT1 may be a therapeutic target of osteosarcoma." (PMID 27813492, 2016). "It is reported that, in osteosarcoma, ALKBH5‐mediated m6A demethylation of lncRNA PVT1 critically contributes to carcinogenesis via acting as an oncogene." (PMID 38098223, 2024). "As same in osteosarcoma, knockdown of ALKBH5 contributed to reducing the stability of LncRNA PVT1 in lung cancer cells." (PMID 37365581, 2023). "In addition, a well-known oncogenic lncRNA plasmacytoma variant translocation 1 (PVT1) was also found to be upregulated in osteosarcoma tissues and cells, whose expression significantly correlated with clinical stage, tumor size, and prognosis of osteosarcoma patients." (PMID 37069649, 2023). "In osteosarcoma, ALKBH5-mediated m6a demethylation of lncRNA PVT1, an oncogene, was up-regulated, where it correlated with clinical stage, tumor size, and poor prognosis." (PMID 35734590, 2022). "In osteosarcoma, ALKBH5 inhibits the degradation of lncRNA PVT1 and leads to the overexpression of lncRNA PVT1." (PMID 35004679, 2021). "Of the different osteosarcoma cell lines, the MG‐63 and SW1353 cell lines displayed the highest expression of lncRNA PVT1 and were selected for the subsequent cell function assays." (PMID 32960485, 2021). "In HCC, PVT1 enhanced autophagy by regulating ATG3 expression via functioning as the sponge of miR-365, whereas in osteosarcoma, PVT1 promoted cell migration and invasion through decoying miR-485." (PMID 33050642, 2020). "Silencing lncRNA PVT1 expression can restore the inhibitory effect of miR-195 on FASN and thus inhibit the proliferation, migration, and invasion of osteosarcoma." (PMID 31757221, 2019). "PVT1 was upregulated and miR-152 was downregulated in the MG63/DOX chemoresistant osteosarcoma cell line." (PMID 31508377, 2019).
osteosarcoma (continued). "PVT1 over expression increased glucose uptake, lactate production, and the expression of HK2 in osteosarcoma cells." (PMID 30083911, 2019). "In our work, we demonstrated that the lncRNA PVT1 is highly expressed in BMSC-derived exosomes, and contributes to the upregulation of PVT1 in osteosarcoma cells (MNNG/HOS, MG-63, and Saos-2 cell lines)." (PMID 31699956, 2019). "The ubiquitination assay was also performed in PVT1-interfering osteosarcoma cells after being co-cultured with BMSC-EXO, and the result demonstrated that PVT1 in exosomes inhibited ubiquitination of ERG protein in osteosarcoma cells." (PMID 31699956, 2019). "In osteosarcoma, the ABCB1 gene was overexpressed in drug-resistant cell lines, but reduced in resistant cell lines where PVT1 has been knocked down." (PMID 31249809, 2019). "Therefore, PVT1 may be used as a lipid therapeutic target for the treatment of osteosarcoma." (PMID 30134946, 2018). "The inhibition of PVT1 had a cascading effect, in that it impeded miR-195 activity that then blocked fatty acid synthase (FASN), and, overall, the invasiveness of human osteosarcoma cell lines consequently decreased." (PMID 28353666, 2017). "Specifically, PVT1 negatively regulated miR-195 in osteosarcoma cells, and silencing PVT1 by siRNA suppressed BCL2, CCND1, and FASN protein expression via miR-195 in osteosarcoma cells." (PMID 27813492, 2016). "On one hand, PVT1 can combine with miR-183 to promote ERG expression, on the other hand, PVT1 can directly combine with ERG to inhibit its ubiquitination degradation, and finally enhance the growth and metastasis of osteosarcoma." (PMID 36309693, 2022). "In addition, we demonstrated that lncRNA PVT1 expression was highly correlated with TNM stage, tumor differentiation, and distant metastasis in patients with osteosarcoma." (PMID 32960485, 2021). "PVT1 mainly acts as a competitive endogenous RNA (ceRNA) to negatively regulate miR-195 in osteosarcoma cells to enhance FASN expression, thereby promoting osteosarcoma cell migration and invasion." (PMID 34803512, 2021). "It has been reported that lncRNA Pvt1, which is usually regarded as an oncogene, influences the expression of HK2, promoting glycolysis, and tumor progression in osteosarcoma and gallbladder cancer through acting as a competitive endogenous RNA to directly bind to miR-497 or miR-143, respectively." (PMID 31850189, 2019). "In osteosarcoma, the induction of the PI3K/AKT pathway was found to be induced by PVT1 expression." (PMID 31249809, 2019). "Since lncRNAs can be packaged in BMSC-derived exosomes and affect tumor growth, we assumed that the upregulation of PVT1 in osteosarcoma cells is partly transported by BMSC-derived exosomes, and regulates downstream target expression thus promoting osteosarcoma growth and metastasis." (PMID 31699956, 2019). "In summary, our findings indicated that BMSC-derived exosomes encapsulate PVTl and transport it into osteosarcoma cells, and the transported PVT1 promotes tumor growth and metastasis by inhibiting ubiquitination and promoting expression of ERG in osteosarcoma cells." (PMID 31699956, 2019). "PVT1 increased the expression levels of BCL2, CCND1 and FASN by inhibiting miR-195 in osteosarcoma." (PMID 27813492, 2016). "In our study, PVT1 expression was higher in osteosarcoma tissues than corresponding noncancerous tissues." (PMID 27813492, 2016). "PVT1 consequently inhibits the apoptosis of osteosarcoma cells via miR-195/BCL2, induces cell-cycle arrest in osteosarcoma cells via miR-195/CCND1, and promotes the migration and invasion of osteosarcoma cells via miR-195/FASN." (PMID 27813492, 2016). "Moreover, silencing PVT1 by siRNA inhibited BCL2, CCND1, and FASN protein expression via miR-195 in osteosarcoma cells, and BCL2 inhibited the si-PVT1#1-induced apoptosis of U2OS cells." (PMID 27813492, 2016).
osteosarcoma (continued). "The mRNA expression level of PVT1 was measured by qRT-PCR and increased in osteosarcoma tissues compared with corresponding noncancerous tissues." (PMID 27813492, 2016). "Therefore, we also studied the relationship between lncRNA PVT1 and EMT in osteosarcoma cells." (PMID 32960485, 2021). "The lncRNA human plasmacytoma variant translocation 1 (PVT1) has been identified as an oncogene and regarded as an indicator for poor survival in pancreatic ductal adenocarcinoma, HCC, and osteosarcoma, although the target genes were not identical in these cancers." (PMID 33050642, 2020). "In addition, our findings indicated that PVT1 in BMSC-derived exosomes promotes osteosarcoma cell proliferation and migration via increasing ERG, an oncogenic protein in osteosarcoma, suggesting interfering PVT1 in exosomes as a therapeutic target of osteosarcoma." (PMID 31699956, 2019). "Furthermore, a recent publication reported that circ-PVT1 could promote the resistance of doxorubicin and cisplatin by regulating ABCB1 in osteosarcoma cells." (PMID 31793989, 2019). "Moreover, we found that the mRNA expression level of PVT1 was upregulated in osteosarcoma cell lines (KHOS, 143b, LM7, U2OS, and MG-63) compared with a normal osteoblast cell line NHost (P < 0.05), and PVT1 expression was higher in U2OS and MG-63 cells than other osteosarcoma cells." (PMID 27813492, 2016). "The different expressions of PVT1 were compared between BMSC-EXO and MNNG-EXO using qRT-PCR, and the result showed an elevator of PVT1 expression in BMSC- EXO, suggesting that the upregulation of PVT1 in osteosarcoma cells may be derived from the transportation of BMSC-EXO." (PMID 31699956, 2019). "We also included MYC/PVT1-neutral cell lines (no amplification and no translocation): U2OS (osteosarcoma), BxPC-3 (pancreatic ductal adenocarcinoma) and DU145 (prostate cancer) as controls." (PMID 40027648, 2025).
ovarian carcinoma (72 papers, 2009 to 2025). A malignant neoplasm originating from the surface ovarian epithelium. "This study investigated the expression profiles of seven specific long noncoding RNAs (lncRNAs)—SNHG7, TUG1, XIST1, PRLB, TLR8-AS1, ZFAS1, and PVT1—associated with epithelial ovarian cancer and their relationship with drug resistance." (PMID 39992529, 2025). "Analogously, lncRNA PVT1 is also overexpressed in ovarian cancer tissues, associated with late-stage disease and a grim prognosis, while facilitating cancer cell growth by suppressing miR-214." (PMID 40999508, 2025). "The PVT1 gene is known as an oncogene, and its overexpression is associated with many types of cancers, including breast and ovarian cancers." (PMID 37185598, 2023). "PVT1 is highly expressed in epithelial ovarian cancer tissues, and the high expression of PVT1 is associated with poor prognosis." (PMID 36869031, 2023). "For example, increased expression of lncRNA plasmacytoma-variant translocation 1 (PVT1) is associated with an advanced stage and a poor prognosis in patients with ovarian cancer." (PMID 39280958, 2022). "PVT1 is associated with other types of cancers such as lung and ovarian cancer and is correlated with the survival of patients." (PMID 35027621, 2022). "In our study, we revealed that PVT1 expression was significantly increased in ovarian cancer tissues which is associated with advanced FIGO stage, lymph‐node metastasis, poor survival rate and high expression of AGO1." (PMID 34288373, 2021). "We reveal that PVT1 expression was significantly increased in ovarian cancer tissues which is associated with advanced FIGO stage, lymph‐node metastasis, poor survival rate, and high expression of AGO1." (PMID 34288373, 2021). "Targeting lncRNA PVT1(Plasmacytoma variant translocation 1) by locked nucleic acid (LNA) rendered the ovarian cancer cells sensitive to cisplatin." (PMID 32575858, 2020). "Inhibition of PVT1 is linked to induction of an apoptotic response and proliferation inhibition of ovarian cancer cell lines [17908964]." (PMID 31379598, 2019). "Both PVT1 copy number gains and overexpression have been implicated in the development of many tumors, including ovarian cancer." (PMID 28430593, 2017). "It had been reported that PVT1 was associated with multiple types of human malignancies, including prostate cancer, pancreatic ductal adenocarcinoma, ovarian cancer etc." (PMID 27634882, 2016). "Functional assays with gain or loss of PVT1 RNA expression demonstrated PVT1’s role in promoting survival and chemoresistance in ovarian cancer cell lines and during intra peritoneal tumor growth, highlighting a pro-metastatic role for Pvt1 in ovarian cancer." (PMID 35820706, 2022). "Moreover, correlation analysis revealed that the PVT1 expression was associated with AGO1 expression in ovarian cancer tissues." (PMID 34288373, 2021). "Notably, PVT1 has been implicated in ovarian cancer tumorigenesis and proposed as a promising diagnostic and therapeutic target, The negative correlation with FAM171A2 may indicate a compensatory or antagonistic function within tumor progression pathways." (PMID 41303609, 2025). "Further, several lncRNAs have been linked with p-53 in ovarian cancer, of which H19, MALAT1, PVT1 and LINC-ROR are upregulated while MEG3 and PANDA are known to be downregulated." (PMID 39912983, 2025). "PVT1 was notably upregulated in resistant cell lines and patient serum samples, supporting its potential role in ovarian cancer progression and treatment resistance." (PMID 39992529, 2025). "lncRNA PVT1 is also frequently overexpressed and enables the proliferation and metastasis of ovarian cancer cells via modulation of miR133a." (PMID 39912983, 2025).
ovarian carcinoma (continued). "LncRNA PVT1 displayed upregulation in cisplatin-resistant ovarian cancer cells and promoted proliferation and migration by increased PD-L1 expression." (PMID 40176927, 2024). "The long noncoding RNA PVT1 is reported to act as an oncogene in several kinds of cancers, especially ovarian cancer (OV)." (PMID 38098223, 2024). "This study reveals a novel regulatory mechanism of ALKBH5 in ovarian cancer: it modifies PVT1 RNA and subsequently stabilizes FOXM1." (PMID 38098223, 2024). "In ovarian cancer, PVT1 has various m6A marks: when high PVT1 levels correlate with cancer, the m6A marks are found low." (PMID 39280246, 2024). "Atezolizumab treatment and knockdown of PVT1 expression showed a synergistic effect on the growth of ovarian cancer and promoted apoptosis of A2780cis cells by downregulating the JAK/STAT3/PD-L1 axis." (PMID 40176927, 2024). "Apart from overexpression of LncRNA 93358 (lncRNA PVT1) in H/R treated rat cardiomyocytes, overexpression of lncRNA PVT1 during the development of ovarian cancer can inhibit apoptosis." (PMID 39651612, 2024). "Experimental studies have shown a high expression level of PVT1 in various cancer types such as breast, colon, gastric, and ovarian cancer." (PMID 36624401, 2023). "Accordingly, PVT1 can function as an oncogenic factor in ovarian cancer cells by regulating the FOXM1 protein level." (PMID 37573419, 2023). "Multivariate analyses have proven that PVT1 can be used as an independent prognostic factor for the recurrence and survival of epithelial ovarian cancer." (PMID 36869031, 2023). "In a recent study conducted using 64 early staged epithelial ovarian cancer tissues and 20 normal ovarian tissues, the expression of two genes—c-MYC and Plasmacytoma Variant Translocation 1 (PVT1)—was studied." (PMID 37110218, 2023). "Here, we demonstrate the role of PVT1, one such stress induced long non-coding RNA, in ovarian cancer growth and metastasis." (PMID 35820706, 2022). "Together, these observations indicate a YAP1 dependency of PVT1 expression with functional correlations in ovarian cancer patients." (PMID 35820706, 2022). "As ovarian cancers are marked by genome amplification, we investigated the correlation between PVT1 amplification and expression." (PMID 35820706, 2022). "Knockdown of lncRNA PVT1 repressed tumor progression via targeting JAK2/STAT3/PD-L1 in cisplatin-resistant ovarian cancer cells." (PMID 36105363, 2022). "Here, we investigate in detail the contexts and mechanism of lncRNA PVT1 expression and metastatic activities particularly in response to various stress factors in ovarian cancer." (PMID 35820706, 2022). "PVT1 inhibits the expression of miR-214 in ovarian cancer cells by regulating the epithelial-mesenchymal transition process and its interaction with EZH2, which promotes the progression of ovarian cancer." (PMID 39280958, 2022). "We demonstrate here for the first time that PVT1 RNA expression is modulated by cell density, hypoxia, and matrix rigidity in both human and mouse ovarian cancer cell lines." (PMID 35820706, 2022). "PVT1 is an amplified and overexpressed lncRNA in ovarian cancer with strong predictive value for survival and response to targeted therapeutics." (PMID 35820706, 2022). "These striking differences indicate that reducing Pvt1 leads to significantly less intraperitoneal tumor burden and demonstrates the critical role of PVT1 in ovarian cancer growth in vivo." (PMID 35820706, 2022). "Assessment of the omentum, ovary, and peritoneal wall, all primary target tissues of metastatic ovarian cancer, revealed that cells expressing Pvt1 (shctrl) had seeded the peritoneum efficiently and invaded into the omental tissue." (PMID 35820706, 2022). "We find a positive correlation between PVT1 and EMT associated genes suggesting a strong correlation between post EMT regulation of PVT1 in ovarian cancer." (PMID 35820706, 2022).